TGFBR2 (transforming growth factor beta receptor 2)
Diseases named in the same sentence as TGFBR2 in open-access papers (continued):
Sharing a sentence is not in itself a finding about the gene and the disease.
cancer (continued). "In some respects, MSS-GS cancers resembled MSI cancers with respect to proximal location, near-diploid genomes and shared driver genes such as TGFBR2, ACVR2A and ARID1A, but there was no increased mutation burden." (PMID 39112709, 2024). "These genes include well annotated tumor-suppressor genes and oncogenes (e.g., TGFBR2 and MYC as well as genes that have never been previously linked to cancer in general, or to increased BC risk (including ADCY3, ATXN7, CFL1 and LPAR2)." (PMID 36991492, 2023). "Additionally, TGFBR2, ACVR2A, and SMAD4 were shown to have high alteration frequencies in pan-cancer." (PMID 36968603, 2023). "Furthermore, the expression of top 5 genes (DCHS1, PRKG1, TGFBR2, TNS1, and TTC28) in the majority of detailed cancer types was shown in the form of heatmap." (PMID 36051999, 2022). "Both miRNAs are upregulated in stem-like PaC cells compared to non-stem cancer cells, suggesting that these miRNAs can play an essential role in stemness regulation, probably via targeting TGFBR2 and DNMT3B in PaC." (PMID 33799952, 2021). "Correlational analysis of clinical OSCC datasets with TGFβ axis differentially expressed genes revealed that the summed expression of FN1, TGFB2, TGFBR2, and TGFBI, dubbed as the CAF index, is a powerful predictor in dichotomized survival analysis for patients of diverse cancer subtypes." (PMID 32605311, 2020). "Taken together, these data suggest that deletion of Pten and Tgfbr2 together specifically in luminal cells results in rapid progression to invasive cancer that is not seen with deletion of Pten alone." (PMID 29782499, 2018). "Similarly, the expression of the type II receptor (TGFBR2) and type III receptor (TGFBR3) were upregulated by the cancer cells in co-culture." (PMID 27819283, 2016). "Several cancer related PCGs were involved such as CDK1/2, BRCA1 and TGFBR2, suggesting that lncRNAs in the core subnetwork may mediate the tumorigenesis by competitively regulating these cancer driver genes in pan-cancers." (PMID 27580177, 2016). "Intriguingly, in some cases, the expression levels of ANGPT1 and TGFBR2 did not correlated with miR-204 levels as is common when compare tissues and cell lines because the heterogeneity of cancer cells." (PMID 27703260, 2016). "Coincidentally, the HPV16 oncoprotein E7 could reduce the expression of TGFBR2 in mouse cervical tissues, suggesting the potential roles of TGF-β receptors in these HPV-related cancers." (PMID 24124460, 2013). "Deregulation of TGFBR2 expression levels and of the inhibitory SMAD7 could influence the normal cellular homeostasis and also influence cancer progression." (PMID 23951322, 2013). "It is also consistent with the concept of an absent upregulation of p21 after abrogation of the TGFβ/SMAD4 axis, which can be explained by knockdown of SMAD4, as in our experiments, but also by absence of TGFBR2, as seen in the cancer samples." (PMID 22761777, 2012). "Absence of TGFBR2 and its downstream targets, including the Smad transcription factors, has been reported in different types of cancers." (PMID 22028892, 2011). "Cadherin 11 (CDH11) and TGFβ receptor 2 (TGFBR2), showing increased abundance in the basal-like cell line MDA-MB231 after co-culture, but not in the MCF7 luminal-like cell line, might suggest a differential influence of NPC interaction with cancer subtypes." (PMID 39232464, 2024). "As in our study, the RNA-seq results showed that PDGFRA was down-regulated, TGFBR2 was up-regulated, and the expression of related apoptosis markers was increased after NR2F2 knockdown, suggesting that NR2F2 promotes the effect of WJ-MSCs in inhibiting cancer cell proliferation." (PMID 36011369, 2022). "The cancer target PDB ID 1RY0 (AKR1C3) showed the highest interactions with the majority of the NCs, followed by 1HFQ (DHFR), 3ZGC (NFE2L2), 4AF3 (AURKB), 4K33 (FGFR3), 5P21 (HRAS), 2I0V (CSF1R), and 3ZIM (PIK3CA) protein targets and least interaction was found with the 1M9Z (TGFBR2) protein." (PMID 36387366, 2022).
cancer (continued). "Furthermore, recent research in cancer cell lines suggested that some miRNAs, such as miR-133b and miR-20b-5p, can inhibit the epithelial-mesenchymal transition (EMT) induced by TGF-β1 by targeting, respectively, TGFBR1 and TGFBR2 genes." (PMID 33905626, 2021). "In addition, non-CPG cancer-driver genes with validated CUVs include TGFBR2 and TGIF1 that are also very likely CPG candidates." (PMID 32778766, 2020). "Of them, miR-93 gained our attention because it shows an oncogenic potential but it has been unclear whether miR-93 could regulate TGFBR2 in cancers, and no studies reported its roles and target genes in NPC." (PMID 24606633, 2014). "The present study is the first to show clearly that miR-655 targets ZEB1 and TGFBR2 inducing inactivation of the TGF-b signaling pathway, involving the miR-200-ZEB1-E-cadherin axis, strongly suggesting a potential role for miR-655 as a prognostic marker and therapeutic agent in human cancers." (PMID 23690952, 2013). "Interestingly, we did not detect any mutation in TGFBR2, MSH3, or MSH6 microsatellite sequences in rectal or sigmoid MSI-H carcinomas in our test series." (PMID 20979647, 2010). "In general, ZNF703 may act as a transcriptional repressor and affect target genes which mediate various aspects of cancer pathophysiology, such as epithelial-mesenchymal transition, adhesion, motility, proliferation and cancer stem cell renewal, CDH1, cadherin-1, CTTND1, p120-catenin and TGFBR2." (PMID 27764785, 2016). "Modulatory activity of PPE in cancer cells OVCAR-3 (but not in HGL5) have been noted by inhibition of TGF-ß2 release, as well as reduction of TGFBR2." (PMID 38027211, 2023). "The fact that we see both dual positive and basal cells at high frequency in invasive cancers, while HGPIN is exclusively luminal suggests that both dual positive and basal cells arise from luminal cells lacking Pten and Tgfbr2." (PMID 29782499, 2018). "The TGF-β pathway was deregulated by alterations to TGFBR1, TGFBR2, ACVR2A, ACVR1B, SMAD2, SMAD3 and SMAD4 in 27 % of non-hypermutated MSS tumours and 87 % of hypermutated cancers." (PMID 27325016, 2016). "Moreover, ZEB1 and TGFBR2, which are essential components of the TGF-b signaling pathway, were identified as direct targets of miR-655, suggesting that the activation of the TGF-b-ZEB1-E-cadherin axis by aberrant downregulation of miR-655 may accelerate cancer progression." (PMID 23690952, 2013). "In addition, several components of TGF-b signaling pathways, TGFBR2, Snail and ZEB1, were reduced directly or indirectly by overexpression of miR-655 in cancer cells treated with or without TGF-b." (PMID 23690952, 2013).
adenocarcinoma (14 papers, 2005 to 2024). A common cancer characterized by the presence of malignant glandular cells. "In this study, we generated a CRC mouse model in which both Tgfbr2 and Apc were inactivated in the colon epithelium; these mutations induce the formation of adenocarcinomas in the proximal colon." (PMID 27835699, 2016). "The mutation rates of Tgfbr2 in the progressed SCCs appeared to increase as compared those detected in the DMBA-treated organoid-derived adenocarcinomas observed in the present study, suggesting an association between squamous cell differentiation and the function of TGFBR2." (PMID 34912374, 2021). "Additionally, in this study, we showed that conditional inactivation of Tgfbr2 in the context of Apc mutation in the colon epithelium results in noninvasive well-differentiated adenocarcinoma, similar to the morphological phenotype observed with Apc mutation alone." (PMID 27835699, 2016). "In the colon epithelium of a CRC mouse model, combined inactivation of APC and TGFBR2 promoted development of adenocarcinoma in the proximal colon, and gasdermin C expression was upregulated by TGFBR2 mutation, resulting in increased CRC cells proliferation." (PMID 36430910, 2022). "The mutations at Vps13d codon 295 and Tgfbr2 codon 549, found in the DMBA-treated organoid-derived adenocarcinomas were observed also in the passaged nodules, diagnosed as SCCs." (PMID 34912374, 2021). "As for Tgfbr2, the mutation rates in the SCCs appeared to increase as compared to those detected in the DMBA-treated organoid-derived adenocarcinomas." (PMID 34912374, 2021). "In conclusion, we generated a CRC mouse model in which inactivation of Tgfbr2 and Apc in the colon epithelium induced the formation of adenocarcinomas." (PMID 27835699, 2016). "In conclusion, combined inactivation of both Apc and Tgfbr2 in the colon epithelium of a CRC mouse model promoted development of adenocarcinoma in the proximal colon." (PMID 27835699, 2016).
infection (13 papers, 2013 to 2025). The state of being infected such as from the introduction of a foreign agent such as serum, vaccine, antigenic substance or organism. "Infection with AAV2/9-BI30-EF1α-DIO-Tgfbr2-3XFLAG-P2A-DsRed-WPREs[Virus(Tgfbr2)] resulted in EC-specific overexpression of the Tgfbr2 protein, increased the expression of EndoMT markers and the generation of E-pericytes." (PMID 40667795, 2025). "RT-qPCR showed that at 12 h after infection, TGFBR2 expression was significantly higher in cells infected with 1 × 107 cfu/mL APEC than in the uninfected control cells." (PMID 39123803, 2024). "Expression of TGFBR2 was rapidly induced upon infection with 1 × 108 CFU/mL APEC and significantly increased over time, with the highest expression at 24 h post infection." (PMID 39123803, 2024). "The constitutive expression of Tgfbr2-FLAG driven by the AAV1-Tgfbr2-FLAG virus ensured that the neonatal infection with this virus resulted in Tgfbr2-FLAG expression both within and outside of tendons." (PMID 31961320, 2020). "With ∼60% infection efficiency, Tgfbr2 expression was reduced by 40–60%." (PMID 27329220, 2016). "The number of activated T cells (subset 2) increased substantially after infection with upregulation of the IFNG, STAT3, STAT4, IL9, FOXP3, and TGFBR1, TGFBR2 genes." (PMID 40573402, 2025). "Expression of TGFBR2 was APEC dose- and infection time-dependent." (PMID 39123803, 2024). "Moreover, ubiquitination of endogenous TGFBR1 and TGFBR2 was markedly elevated by the overexpression of SMURF2WT, but it was decreased by the enforced infection of SMURF2T249A in TGS-01 GSCs." (PMID 35017630, 2022). "We found that Tgfbr2 mRNA expression did not change significantly; however, Tgfbr2 protein levels were significantly downregulated at 5-hour post-infection." (PMID 30413725, 2018). "In the present study, TGFB1 mRNA was not increased by the infection with Ad-TGFBR2." (PMID 23457527, 2013). "Infection of YFP+CD34+ SCC cells with the rescue construct, but not the empty vector, efficiently restored Tgfbr2 mRNA expression." (PMID 28219480, 2017).
connective tissue disorder (10 papers, 2012 to 2026). A disease involving the connective tissue. "Loeys‐Dietz syndrome (LDS) is an autosomal dominant connective tissue disorder caused by pathogenic variants in TGFBR1 or TGFBR2." (PMID 41426201, 2026). "Loeys‐Dietz syndrome (LDS) is a systemic connective tissue disorder caused by pathogenic variants in TGFBR1 or TGFBR2, characterized by arterial tortuosity, aneurysms, and skeletal and craniofacial abnormalities." (PMID 41426201, 2026). "The identification of TGFBR2 mutations in patients with MFS2 provided the first direct link between a human connective tissue disorder and abnormal TGF-β signaling." (PMID 22259224, 2012). "Individual II:3 underwent testing using a commercial panel of 92 connective tissue disorder genes, revealing a variant in TGFBR2 (NM_003242.6 (TGFBR2):c.412T>G) classified as likely pathogenic by a commercial genetic testing lab with a proprietary variant calling software based on ACMG guidelines." (PMID 39737004, 2024). "LDS is a rare, multi-system connective tissue disorder caused by an autosomal dominant, heterozygous mutation of TGFBR1 or TGFBR2." (PMID 33289867, 2020). "For this reason, the same revised Ghent nosology recommends supplementing genetic tests with analyses of TGFBR1, TGFBR2, COL3A1, and collagen biochemistry, especially when symptoms of MFS overlap with those of other connective tissue disorders." (PMID 37688493, 2024). "High throughput sequencing of 34 genes for hereditary connective tissue disorders did not identify any mutation in FLNB, but did identify a de novo missense mutation in TGFBR2 and a nonsense mutation in COL2A1 that was also present in his unaffected father." (PMID 30170566, 2018).
cardiovascular disease (5 papers, 2013 to 2020). "TGF-β receptor 2 (Tgfbr2) has been functionally associated with cardiovascular diseases and miR-204 was observed to directly inhibit Tgfbr2 mRNA in a direct manner both in HPASM cells and in a luciferase assay, thus extending the potential roles for miR-204 in cardiac pathogenesis." (PMID 23300973, 2013). "Heterozygous mice did not display a cardiovascular disease phenotype, which is in line with previous findings in both Tgfbr1 and Tgfbr2 knock-out mouse models." (PMID 24587008, 2014).
breast (4 papers, 2012 to 2020). "Thus, the eight gene panel (CXCL12, CK7, CDH1, CTNNB1, CD44v6, MUC16, TGFBR2 and HIF1A) can be a highly significant predictor of liver metastasis outcome independent of the standard prognostic criteria." (PMID 30383826, 2018).
neurological disease (4 papers, 2010 to 2025). "The binding of HSA to astrocyte TGFBR1 and TGFBR2 following BBB disruption is associated with seizures in several neurological diseases." (PMID 20529383, 2010). "Further studies are warranted to elucidate the specific interactions between miR-34b and TGFBR2 in brain injury, potentially leading to the development of targeted therapies for brain injury and related neurological disorders." (PMID 39129166, 2025).
vascular disorder (3 papers, 2014 to 2024). A general term used to describe any disease affecting blood vessels]. "Similar to other conditions known as TGF-β vasculopathies (MFS, which is caused by FBN1 mutations and LDS, which is caused by TGFBR1, TGFBR2, SMAD3 and TGFB2 mutations), the SLC2A10 loss of function activates the TGF-β signaling pathway." (PMID 25373504, 2014).
genetic disorders (2 papers, 2017 to 2025). "Since TGFBR2-R497X is a nonsense mutation and mutations in the same residue as TGFBR2-D524N have been detected in inherited diseases, it indicates loss of function for both cases." (PMID 28426742, 2017).
TGFBR2 also shares sentences with these, for which no sentence is quoted: vascular Ehlers-Danlos syndrome (5 papers); Ehlers-Danlos syndrome (4); invasive breast carcinoma (4); metastatic tumors (4); acute myeloid leukemia (3); fibrosis (3); hereditary non-polyposis colon cancer (3); Multiple myeloma (3); renal cell carcinoma (3); sudden cardiac arrest (3); Ureteral obstruction (3); acute pancreatitis (2); ascending aortic aneurysm (2); autosomal dominant polycystic kidney disease (2); chronic kidney disease (2); colorectal adenoma (2); coronary artery aneurysm (2); dissection (2); endothelial dysfunction (2); Hepatic steatosis (2); Hypertension (2); Kawasaki disease (2); kidney cancer (2); lung disease (2); mammary adenocarcinoma (2); myocardial infarction (2); neurodegenerative disease (2); osteomyelitis (2); rectal cancer (2); scrub typhus (2).
A further 125 diseases each share a sentence with TGFBR2 in 2 papers or fewer.